AMOTL2 (angiomotin like 2)
Description:
Regulates the translocation of phosphorylated SRC to peripheral cell-matrix adhesion sites. Required for proper architecture of actin filaments. Plays a role in coupling actin fibers to cell junctions in endothelial cells and is therefore required for correct endothelial cell morphology via facilitating transcellular transmission of mechanical force resulting in endothelial cell elongation (By similarity). Required for the anchoring of radial actin fibers to CDH1 junction complexes at the cell membrane which facilitates organization of radial actin fiber structure and cellular response to contractile forces. This contributes to maintenance of cell area, size, shape, epithelial sheet organization and trophectoderm cell properties that facilitate blastocyst zona hatching. Inhibits the Wnt/beta-catenin signaling pathway, probably by recruiting CTNNB1 to recycling endosomes and hence preventing its translocation to the nucleus. Participates in angiogenesis. Activates the Hippo signaling pathway in response to cell contact inhibition via interaction with and ubiquitination by Crumbs complex-bound WWP1. Ubiquitinated AMOTL2 then interacts with LATS2 which in turn phosphorylates YAP1, excluding it from the nucleus and localizing it to the cytoplasm and tight junctions, therefore ultimately repressing YAP1-driven transcription of target genes. Acts to inhibit WWTR1/TAZ transcriptional coactivator activity via sequestering WWTR1/TAZ in the cytoplasm and at tight junctions. Regulates the size and protein composition of the podosome cortex and core at myofibril neuromuscular junctions. Selectively promotes FGF-induced MAPK activation through SRC. May play a role in the polarity, proliferation and migration of endothelial cells.
Synonyms: LCCP
Tractability: Antibody: its Gene Ontology location is reachable by antibodies, with medium confidence. PROTAC: UniProt records ubiquitination sites on it; ubiquitination databases record sites on it; its protein half-life has been measured.
Gene: Protein-coding gene on chromosome 3 (134,355,347 to 134,375,479, reverse strand). Ensembl gene ENSG00000114019.
Subcellular location: Recycling endosome; Cytoplasm; Cell projection, podosome; Cell junction
Subcellular location (Human Protein Atlas): Cell Junctions
Pathways (Reactome):
Signal Transduction: Signaling by Hippo
Gene Ontology:
Molecular function: protein binding; actin filament binding; identical protein binding; protein-containing complex binding
Biological process: positive regulation of protein localization; actin cytoskeleton organization; angiogenesis; endothelial cell morphogenesis; establishment of cell polarity involved in ameboidal cell migration; hippo signaling; negative regulation of transcription by RNA polymerase II; regulation of cell migration
Cellular component: anchoring junction; cytoplasm; podosome; bicellular tight junction; cell junction; cytoplasmic vesicle; cytosol; plasma membrane; recycling endosome; apical plasma membrane
Genetic constraint (gnomAD): Loss-of-function variants: 33 observed, 76.87 expected, observed/expected ratio (o/e) 0.43, 90% interval 0.32 to 0.57. The upper end of that interval is the gene's LOEUF score, 0.57, which puts it in group 2 of 6, group 1 being the genes least tolerant of losing a copy. Missense variants: 983 observed, 1,051 expected, observed/expected ratio (o/e) 0.94, 90% interval 0.89 to 0.99. Synonymous variants: 422 observed, 438.67 expected, observed/expected ratio (o/e) 0.96, 90% interval 0.89 to 1.04.
Homologues: Orthologues: chimpanzee AMOTL2 (99% identical), macaque AMOTL2 (98% identical), dog AMOTL2 (92% identical), pig AMOTL2 (92% identical), guinea pig AMOTL2 (90% identical), rat Amotl2 (89% identical), mouse Amotl2 (89% identical), rabbit AMOTL2 (87% identical), tropical clawed frog amotl2 (54% identical), zebrafish amotl2a (48% identical), zebrafish amotl2b (37% identical). Paralogues in human: AMOT (44% identical), AMOTL1 (44% identical).
Diseases named in the same sentence as AMOTL2 in open-access papers:
AMOTL2 is named in the same sentence as 31 diseases in open-access papers, as found by Europe PMC text mining. Sharing a sentence is not in itself a finding about the gene and the disease. The quoted sentences say what the papers report.
pancreatic cancer (6 papers, 2020 to 2024). "In depleted cells, UCA1 acts as an exosomal lncRNA to promote angiogenesis in pancreatic cancer via the miR-96-5p/AMOTL2 axis." (PMID 36871072, 2023). "Exosomes secreted by hypoxic pancreatic cancer promotes EC migration and tube formation through upregulation of angiomotin-like protein 2 (AMOTL2)." (PMID 33363174, 2020). "Promotes angiogenesis and tumor growth through sponging miR-96-5p to upregulate angiomotin-like protein 2 (AMOTL2) in pancreatic cancer." (PMID 33363174, 2020).
breast carcinoma (4 papers, 2018 to 2021). "In luminal breast cancer MCF7 cell line, downregulation of MAGI1 is associated with an increased accumulation of AMOTL2 (Angiomotin Like 2) and of E-cadherin, and to enhanced cell proliferation, but not cell migration or invasiveness." (PMID 34503076, 2021). "In breast cancer, AMOTL2 increased LATS kinase activity leading to the suppression of metastasis of tumor cells." (PMID 33658392, 2021). "AMOTL1 has been shown to act as an oncogene in breast cancer and cervical cancer, and AMOTL2 has been reported to act as an oncogene in breast cancer and suppressor glioblastoma carcinogenesis." (PMID 31330820, 2019). "AMOTL2 is also a promoter of breast cancer progression while it suppressed glioblastoma carcinogenesis." (PMID 29650031, 2018). "Interestingly, suppressed and over-expressed AMOTL2 was verified in breast cancer and brain cancer respectively." (PMID 29650031, 2018). "However, in breast cancer, high expression level of AMOTL2 was significantly negative correlated with clinical grade." (PMID 33658392, 2021).
colon cancer (4 papers, 2017 to 2024). "Deregulated AmotL2 expression in tumor and metastasized areas during tumor progression confirms what recently has been well established in colon cancer tumors, AmotL2 expression correlates with loss of polarity by means of hypoxia activated c-Fos, leading to loss of tissue architecture." (PMID 28441737, 2017). "A previous study of our group reported changes in AmotL2 expression in colon cancer and its liver metastases after treatment with OxPt-based chemotherapy." (PMID 39335466, 2024). "In colon cancer, AMOTL2 functions as an oncogene that promotes cell growth and invasion by disrupting the apical-basal polarity." (PMID 38956029, 2024). "These facts show a “basal” inflammatory state of the ENS accompanied with an elevation of AmotL2 in colon cancer and an increased inflammatory state with OxPt-based chemotherapy." (PMID 39335466, 2024). "This isoform of AmotL2 is expressed in invasive breast and colon tumors and promotes invasion in vitro and in vivo." (PMID 37681890, 2023). "In this study, we analyzed the expression of AmotL2 in normal colon tissue in greater detail by performing immunohistochemical staining on samples resected from colon cancer patients." (PMID 37681890, 2023). "Our results indicate a relationship between TNF-α and AmotL2 expression, either in healthy areas of the colon from patients suffering from colon cancer resected previous to OxPt chemotherapy or in healthy areas of resected colon from patients after chemotherapy." (PMID 39335466, 2024).
glioblastoma (3 papers, 2018 to 2024). The most malignant astrocytic tumor (WHO grade IV). "In glioblastoma, phosphorylation of AMOTL2 by the mTORC2 kinase enhances YAP1 signaling, leading to cancer growth and invasiveness." (PMID 29650031, 2018). "Moreover, low expression of AMOTL2 facilitates glioblastoma proliferation and metastasis through regulating β‐catenin nuclear localization." (PMID 38956029, 2024). "Phosphorylation/inactivation of AMOTL2 enhances transcription of YAP-targeting genes and promotes glioblastoma (GBM) growth, motility, and invasion in vitro, as well as GBM growth in vivo." (PMID 35163745, 2022).
colorectal cancer (2 papers, 2017 to 2023). A primary or metastatic malignant neoplasm that affects the colon or rectum. "We report the pattern of cellular and subcellular expression of scaffoldins angiomotin-like 2 (AmotL2), FK506 binding protein 5 (FKBP51) and IQ motif containing GTPase-activating protein 1 (IQGAP1) in colorectal cancer (CRC) and metastases in liver resected after oxaliplatin-based chemotherapy (CT)." (PMID 28441737, 2017).
hepatocellular carcinoma (2 papers, 2017 to 2021). A malignant tumor that arises from hepatocytes. "Besides, when downregulated, AMOTL2 enhanced tumor cells growth, migration and angiogenesis via Hippo pathway in hepatocellular carcinoma." (PMID 33658392, 2021). "Altogether, the present data indicate that XAV-939 and G007-LK Tankyrase inhibitors could suppress proliferation of hepatocellular carcinoma cells and downregulate YAP/TAZ by stabilizing AMOTL1 and AMOTL2 proteins, thus representing new potential anticancer drugs against hepatocellular carcinoma." (PMID 28877210, 2017).
abdominal aortic aneurysm (1 paper, 2023). Enlargement and ballooning of the vessel that supplies arterial blood to the abdomen, pelvis and legs. "The deletion of AmotL2 was found to provoke inflammation and abdominal aortic aneurysms, suggesting a linkage between junctional mechanotransduction and vascular disease." (PMID 39195920, 2023). "Furthermore, the endothelial deficit of AmotL2 in mice fed normal diet provoked a pro-inflammatory response and abdominal aortic aneurysms (AAAs)." (PMID 39195920, 2023).
aneurysm (1 paper, 2023). Bulging or ballooning in an area of an artery secondary to arterial wall weakening. "Next, we wanted to study the influence of AmotL2 deletion in an established murine model of aneurysm formation." (PMID 39195920, 2023).
asthma (1 paper, 2023). "This indicates that Amotl2 plays an important role in airway remodeling of asthma." (PMID 37221600, 2023).
atherosclerosis (1 paper, 2024). A disease characterized by the build-up of fatty material and calcium deposition in the arterial wall resulting in partial or complete occlusion of the arterial lumen. "Collectively, these analyses nominate rs9876658 as a causal regulator of AMOTL2 expression in SMCs but not ECs and implicate this gene as a novel candidate for atherosclerosis." (PMID 39606421, 2024).
Atrophy (1 paper, 2015). Any weakening or degeneration, especially through lack of use. "Furthermore, anti-angiogenic regulators such as Angiomotin like 2 (Amotl2) and Thrombospondin 2 (Thbs2) were highly expressed in the atrophy group at day 7 and slightly higher at day 42 compared to the control group." (PMID 25910190, 2015).
cardiomyopathy (1 paper, 2023). A disease of the heart muscle or myocardium proper. "They observed an increase promoter methylation of three genes associated with cardiac angiogenesis in cardiomyopathy, PECAM1, ARHGAP24, and AMOTL2, suggesting that DNA methylation induces altered gene expression in cardiomyopathy." (PMID 37008904, 2023).
hemorrhagic fever (1 paper, 2024). An infectious disease caused by certain viruses or bacteria that can damage the walls of tiny blood vessels, making them leak, and can hamper the blood's ability to clot and cause severe, life-threatening illness. "Considering that endothelial cell damage, disrupted vascular permeability, and cell dysfunction are factors associated with filovirus hemorrhagic fevers, a potential role of MARV-induced AMOTL2 overexpression for the induction of endothelial cell damage is conceivable." (PMID 40295691, 2024).
inflammatory bowel disease (1 paper, 2024). A spectrum of small and large bowel inflammatory diseases of unknown etiology. "The parallel increase in inflammation marker TNF-α, along with AmotL2 expression in EGCs, varying from low TNF-α/medium AmotL2 signal in controls to high TNF-α/high AmotL2 after treatment, are interesting evidence that might indicate the involvement of EGCs in inflammatory bowel disease." (PMID 39335466, 2024).
invasive ductal carcinoma (1 paper, 2021). "Interestingly, a short isoform of AMOTL2 (AMOTL2 p60 in contrast to the long AMOTL2 p100) was reported overexpressed in in situ and invasive ductal carcinoma cells." (PMID 33707576, 2021).
lung adenocarcinoma (1 paper, 2021). A carcinoma that arises from the lung and is characterized by the presence of malignant glandular epithelial cells. "Univariate and multivariate analyses results showed the low expressions of AMOTL2 was an independent risk factor for predicting overall survival in lung adenocarcinoma." (PMID 33658392, 2021). "The result of univariate and multivariate analyses showed that AMOTL2 could be considered as an independent risk factor in lung adenocarcinoma." (PMID 33658392, 2021). "Notably, AMOTL2, the target gene of exosomal miR-149-5p, was significantly downregulated in lung adenocarcinoma and may be considered as an independent risk factor of poor survival." (PMID 33658392, 2021). "In lung adenocarcinoma cells, AMOTL2 downregulation reversed the promoting effect of miR-149-5p on A549 cells growth and the inhibition effect of miR-149-5p on A549 cells apoptosis." (PMID 33658392, 2021). "Our results demonstrated that exosomal miR-149-5p activated the growth and reduced apoptotic rate of tumor cells in lung adenocarcinoma via targeting AMOTL2." (PMID 33658392, 2021). "Numerous studies had demonstrated the biological functions of TGF-β signaling pathway and Wnt/β signaling pathway in lung adenocarcinoma, indicating that AMOTL2 played a vital role in the occurrence and development of lung adenocarcinoma." (PMID 33658392, 2021). "GSEA results indicated that AMOTL2 could regulate the development of lung adenocarcinoma via TGF-β signaling pathway and Wnt/β signaling pathway." (PMID 33658392, 2021). "However, the effect of AMOTL2 on lung adenocarcinoma is incompletely understood." (PMID 33658392, 2021). "Moreover, GSEA results indicated that AMOTL2 could regulate the progression of lung adenocarcinoma via TGF-β signaling pathway and Wnt/β signaling pathway." (PMID 33658392, 2021). "Thus, it is urgent to explore the detailed biological mechanism of AMOTL2 in lung adenocarcinoma." (PMID 33658392, 2021).
lung carcinoma (1 paper, 2015). "First, we validated two of the most significantly altered genes, ASCL1 and AMOTL2, in a subset of 20 subjects (13 lung cancer patients and 7 controls)." (PMID 25705890, 2015).
medulloblastoma (1 paper, 2020). A malignant, invasive embryonal neoplasm arising from the cerebellum. "Survival analysis revealed that high expression of AMOTL2 was significantly associated with a favourable prognosis in paediatric medulloblastoma patients in Group 3 and Group 4, which was consistently observed in the two independent cohorts." (PMID 33292274, 2020). "Importantly, low expression of AMOTL2 was significantly associated with overall poor survival in paediatric Group 3 and Group 4 medulloblastoma patients." (PMID 33292274, 2020).
mesothelioma (1 paper, 2023). A usually malignant and aggressive neoplasm of the mesothelium which is often associated with exposure to asbestos. "In the Hippo pathway-proficient cell line HepG2, TEAD inhibition led to a partial reduction in AMOTL2, CTGF, and CYR61 mRNA expression, as expected and consistent with the partial efficacy we observed in Hippo-defective mesothelioma cell lines." (PMID 38139762, 2023).
non-small cell lung carcinoma (1 paper, 2021). A group of at least three distinct histological types of lung cancer, including non-small cell squamous cell carcinoma, adenocarcinoma, and large cell carcinoma. "In non-small cell lung cancer, AMOTL2 functioned as negative regulator of tumor cells proliferation via AMOTL2/PPP2R2A/JUN axis." (PMID 33658392, 2021).
tumor (27 papers, 2006 to 2025). "Amotl2, which encodes a Motin family member, Angiomotin-like 2, is a tumor suppressor that negatively regulates the YAP and TAZ function via AMOT-mediated tight junction localization." (PMID 37414763, 2023). "In tumor associated blood vessels (v), high levels of AmotL2 specific labeling were observed in nucleus and cytoplasm of endothelial cells (Figure 3B2,B3)." (PMID 28441737, 2017). "Additionally, hypoxic tumor-derived exosomal lncRNA urothelial cancer-associated 1 (UCA1) was shown to promote angiogenesis via miRNA-96-5p/AMOTL2 (angiomotin-like 2) in PaCa." (PMID 34243775, 2021). "Amotl2 was described with a dual tumour suppressive function by targeting both Yap (known as anti‐apoptosis transcription factor) and Akt (which contributes to impaired apoptosis in cancer)." (PMID 40275631, 2025). "A family of proteins that has recently come under scrutiny for their role in tumor development are angiomotins, namely Angiomotin-like protein 2, or AmotL2." (PMID 38594748, 2024). "A potential explanation is that AMOTL2 includes two isoforms of p60 and p100, and the short isoform of AMOTL2 p60 for an oncogenic role is in contrast with the long isoform of AMOTL2 p100 for tumor suppression." (PMID 38956029, 2024). "In a collaborative effort with the human protein atlas consortium (HPA), we conducted an analysis of AmotL2 expression across various tumor types." (PMID 38594748, 2024). "Consistently, exosomal miR-149-5p promoted growth and inhibited apoptosis of tumor cells via targeting AMOTL2 gene." (PMID 33658392, 2021). "Further, the results of expression analyses in TCGA-LUAD revealed that miR-149-5p was a negative regulator of AMOTL2, indicating that exosomal miR-149-5p regulated metastasis of tumor cells by targeting AMOTL2 gene." (PMID 33658392, 2021). "ANKRD1 was abundant in the tumour centre, while AMOTL2 and AXL were higher at periphery, where C3-positive microglia were also observed." (PMID 32404936, 2020). "q-PCR results showed that the YAP (Cyr61, Amotl2, and Ankrd1) and ERK1/2 target genes (c-Myc and ELK-1) were elevated in WISP2 deficient tumor samples." (PMID 32711570, 2020). "For example, AMOT, AMOTL1, as well as AMOTL2 exert both oncogene or tumor suppressive gene in different cancer types." (PMID 29650031, 2018). "The variation levels and the subcellular redistribution of AmotL2 shown in this study in tumor cells, metastasis and blood vessels and adjacent cells are indicative of its involvement in the CRC tumorigenesis and progression processes." (PMID 28441737, 2017). "AMOTL2, the most abundant angiomotin in both resistant H2052 and sensitive H2373 tumor cells, showed lower and less durable stabilization in H2052 cells in response to XAV939." (PMID 27144834, 2016). "Using multivariate analysis of the following factors, nodal status, tumour grade, angiomotin, angiomotin-like-1 and angiomotin-like-2, we have found that nodal status (p = 0.0185) and angiomotin transcript (p = 0.031) were independent survival factors." (PMID 16430777, 2006). "Given the localization of AmotL2 to areas of cell shedding in both normal and tumor tissues, we hypothesized that p60AmotL2 could be involved in the process of apical extrusion." (PMID 37681890, 2023). "In our study, AMOTL2 was found to be tumor suppressor gene in TCGA-LUAD cohort." (PMID 33658392, 2021). "In PC, hypoxic exosome-mediated UCA1 could promote tumor angiogenesis and accelerate tumor growth via the miR-96-5P/AMOTL2/ERK1/2 axis and serve as a novel therapeutic target." (PMID 34124046, 2021). "The apoptotic assay showed that the promotive effect of miR-149-5p inhibitor on the apoptotic abilities of tumor cells could be rescued by the inhibition of AMOTL2." (PMID 33658392, 2021). "Moreover, we explored that exosomal miR-149-5p accelerated growth and suppressed apoptosis of tumor cells via inhibiting AMOTL2." (PMID 33658392, 2021). "Particularly, AMOTL2 played an important regulatory role in tumor microenvironment." (PMID 33658392, 2021).